EOGT (EGF domain specific O-linked N-acetylglucosamine transferase)
Description:
Catalyzes the transfer of a single N-acetylglucosamine from UDP-GlcNAc to a serine or threonine residue in extracellular proteins resulting in their modification with a beta-linked N-acetylglucosamine (O-GlcNAc). Specifically glycosylates the Thr residue located between the fifth and sixth conserved cysteines of folded EGF-like domains.
Synonyms: AER61; C3orf64; EOGT1; FLJ33770; AOS4
Tractability: Antibody: UniProt predicts a signal peptide or a membrane-spanning region. PROTAC: its protein half-life has been measured.
Gene: Protein-coding gene on chromosome 3 (68,975,217 to 69,013,684, reverse strand). Ensembl gene ENSG00000163378.
Subcellular location: Endoplasmic reticulum lumen
Subcellular location (Human Protein Atlas): Nuclear membrane; Nucleoplasm; Cytosol
Gene Ontology:
Molecular function: protein O-acetylglucosaminyltransferase activity; glycosyltransferase activity
Biological process: protein O-linked glycosylation
Cellular component: endoplasmic reticulum lumen
Genetic constraint (gnomAD): Loss-of-function variants: 23 observed, 29.07 expected, observed/expected ratio (o/e) 0.79, 90% interval 0.57 to 1.12. The upper end of that interval is the gene's LOEUF score, 1.12, which puts it in group 4 of 6, group 1 being the genes least tolerant of losing a copy. Missense variants: 400 observed, 375.19 expected, observed/expected ratio (o/e) 1.07, 90% interval 0.98 to 1.16. Synonymous variants: 149 observed, 137.79 expected, observed/expected ratio (o/e) 1.08, 90% interval 0.95 to 1.24.
Homologues: Orthologues: chimpanzee EOGT (99% identical), macaque EOGT (97% identical), dog EOGT (93% identical), pig EOGT (92% identical), rabbit EOGT (91% identical), guinea pig EOGT (90% identical), mouse Eogt (88% identical), rat Eogt (87% identical), tropical clawed frog eogt (68% identical), zebrafish eogt (65% identical), Drosophila melanogaster Eogt (45% identical), Caenorhabditis elegans H12D21.10 (40% identical). Paralogues in human: POMGNT2 (21% identical).
Diseases named in the same sentence as EOGT in open-access papers:
EOGT is named in the same sentence as 29 diseases in open-access papers, as found by Europe PMC text mining. Sharing a sentence is not in itself a finding about the gene and the disease. The quoted sentences say what the papers report.
Adams-Oliver syndrome (3 papers, 2017 to 2022). Adams-Oliver Syndrome (AOS) is a rare disorder characterized by the combination of congenital limb abnormalities and scalp defects, often accompanied by skull ossification defects. "For example, EOGT is an enzyme that attaches a sugar molecule onto the Notch receptor, and mutations in the gene that encodes EOGT are found in people with Adams-Oliver syndrome – a rare condition that causes their skin and limbs to fail to develop properly." (PMID 28395734, 2017).
autoimmune hepatitis (2 papers, 2021 to 2025). Hepatitis caused by autoantibodies. "A preliminary study by our group revealed that the deficiency of EGF domain-specific O-linked N-acetylglucosamine transferase (EOGT) impaired regulatory T-cell differentiation in autoimmune hepatitis." (PMID 35069551, 2021). "Furthermore, EOGT has been implicated in HCC, pancreatic cancer, and autoimmune liver diseases; however, the underlying molecular mechanisms remain elusive." (PMID 40299340, 2025).
pancreatic cancer (2 papers, 2024 to 2025). "In pancreatic cancer models, EOGT has been shown to form a complex with SHCBP1, leading to enhanced NOTCH1 modification and subsequent tumor progression." (PMID 40299340, 2025).
atherosclerosis (1 paper, 2025). A disease characterized by the build-up of fatty material and calcium deposition in the arterial wall resulting in partial or complete occlusion of the arterial lumen. "The results showed a significant upregulation of migrasome‐associated genes, including TSPAN4, TSPAN7, EOGT, and PIGK, in the model group, further supporting the high expression of migrasomes in atherosclerosis." (PMID 40548932, 2025).
atrial septal defect (1 paper, 2025). Interauricular communication is a congenital malformation characterized by a communication between the atrial chambers of the heart. "Variants in genes associated with atrial septal defects and ventricular septal defects (e.g., DOCK6, EOGT, EP300, EVC, EVC2, and SEMA3C) have also been identified in patients." (PMID 41153298, 2025).
breast carcinoma (1 paper, 2025). "Notably, EOGT expression was upregulated in the TNFα-treated mouse breast cancer cell line 4T1." (PMID 40299340, 2025).
cancer (5 papers, 2021 to 2025). A tumor composed of atypical neoplastic, often pleomorphic cells that invade other tissues. "Additionally, in tumors such as KIPAN, SKCM, and ACC, EOGT expression was positively associated with distant metastasis, further supporting its involvement in aggressive cancer phenotypes." (PMID 40299340, 2025). "In summary, through pan-cancer analyses, we identified EOGT as a key oncogene significantly upregulated in HCC and associated with poor prognosis." (PMID 40299340, 2025). "Data from the TIMER database revealed that EOGT expression was upregulated in seven cancer types, including HCC, but it showed a pattern of decreasing expression in the other seven cancer types." (PMID 35069551, 2021). "There are three marker proteins (NDST1, PIGK, and EOGT) of migrasome expressed in cancer." (PMID 38748047, 2024). "The results showed that ITGA5, NDST1, CPQ, ITGB1, PIGK, EOGT, and TSPAN4 had amplifications or deletions in most cancers." (PMID 36405728, 2022). "Additionally, EOGT positively correlated with tumor stemness in KIRP, LGG, and GBMLGG, suggesting its role in regulating DNA damage repair and cancer progression." (PMID 40299340, 2025). "Notably, KEGG results showed that EOGT upregulated genes were mainly enriched in the PI3K–Akt signaling pathway, focal adhesion, platelet activation, proteoglycans in cancer, cGMP–PKG signaling pathway, and so on." (PMID 35069551, 2021).
tumor (3 papers, 2021 to 2025). "Additionally, elevated EOGT expression was correlated with advanced tumor staging and linked to poor overall survival and relapse-free survival, serving as a significant unfavorable prognostic indicator in HCC patients." (PMID 35069551, 2021). "Notably, EOGT expression showed a significant positive correlation with advanced tumor grades in HNSC, STAD, GBMLGG, and LGG, suggesting its potential role in promoting tumor progression." (PMID 40299340, 2025). "Notably, analysis of GSE109211 data from the BEST database demonstrated significant upregulation of EOGT in tumor tissue samples from sorafenib non-responders." (PMID 40299340, 2025).
genetic disorders (1 paper, 2025). "EOGT deficiency has been linked to genetic disorders, including Adams–Oliver syndrome, primarily through its modification of NOTCH receptors and subsequent regulation of downstream signaling pathways." (PMID 40299340, 2025).
EOGT also shares sentences with these, for which no sentence is quoted: 22q11.2 deletion syndrome (1 paper); aplasia cutis congenita (1); Beckwith-Wiedemann syndrome (1); bladder urothelial carcinoma (1); breast-invasive carcinoma (1); cholangiocarcinoma (1); head and neck squamous cell carcinoma (1); Jacobsen syndrome (1); Kabuki syndrome (1); kidney chromophobe (1); liver cancer (1); lung adenocarcinoma (1); lung squamous cell carcinoma (1); Oliver syndrome (1); prostate adenocarcinoma (1); Stroke (1); thyroid carcinoma (1); Turner syndrome (1); uterine corpus endometrial carcinoma (1); ventricular septal defect (1).